U3 (Small nucleolar RNA U3 )
Synonyms: LOC124905292
Gene: Small nucleolar RNA gene on chromosome X (122,840,426 to 122,840,645, forward strand). Ensembl gene ENSG00000212321.
Gene Ontology:
Biological process: RNA processing
Cellular component: nucleolus
Homologues: Orthologues: chimpanzee U3 (99% identical), macaque U3 (85% identical), rabbit U3 (60% identical). Paralogues in human: SNORD3P1 (81% identical), U3 (80% identical), U3 (79% identical), U3 (76% identical), SNORD3H (76% identical), SNORD3E (75% identical), U3 (75% identical), U3 (73% identical), SNORD3D (73% identical), SNORD3G (73% identical), U3 (72% identical), U3 (71% identical), and 13 more.